LRRK2 (leucine rich repeat kinase 2)
Diseases named in the same sentence as LRRK2 in open-access papers (continued):
Sharing a sentence is not in itself a finding about the gene and the disease.
fibromatosis (1 paper, 2019). A poorly circumscribed neoplasm arising from the soft tissues. "LRRK2 and CTNNB1 were also reported to interact with the Wnt pathway in fibromatosis." (PMID 31178673, 2019).
fungal infection (1 paper, 2018). "Since, the Ca2+/NFAT/IL-2 axis has been previously found to regulate DC response to the fungus Aspergillus, we have investigated the role played by the kinase LRRK2 during fungal infection." (PMID 29472933, 2018). "Since, we have previously shown that A. fumigatus swollen conidia, more than ungerminated conidia, induces Ca2+/NFAT/IL-2 pathway in DCs, here we went to study the regulation of LRRK2 in response to fungal infection." (PMID 29472933, 2018).
glaucoma (1 paper, 2022). Increased pressure in the eyeball due to obstruction of the outflow of aqueous humor. "LRRK2 is reported to regulate actin filaments in many models, e.g. LRRK2 regulates the F-actin/G-actin ratio of Schlemm's canal endothelium in a rat glaucoma model." (PMID 34918122, 2022).
Gliosis (1 paper, 2023). Gliosis is the focal proliferation of glial cells in the central nervous system. "Accordingly, the Morari group reported that LRRK2 PF and MLi2 inhibitors protected from 1-methyl-4-phenyl-1,2,5,6-tetrahydropyridine (MPTP)-induced neurotoxicity and gliosis." (PMID 37443833, 2023).
Glucose intolerance (1 paper, 2023). Glucose intolerance (GI) can be defined as dysglycemia that comprises both prediabetes and diabetes. "In the present study, we investigated the effect of LRRK2 on high‐fat diet (HFD)‐induced glucose intolerance using Lrrk2‐knockout (KO) mice." (PMID 37845194, 2023). "Nevertheless, it seems certain that LRRK2 is involved in abnormal glucose tolerance, and hence, we propose that inhibition of the LRRK2 kinase activity targeted to the improvement of glucose intolerance may be a new strategy for the treatment of glucose metabolism disorders." (PMID 37845194, 2023).
Hand tremor (1 paper, 2013). An unintentional, oscillating to-and-fro muscle movement affecting the hand. "The British white woman who carried the LRRK2 G2019S mutation and the heterozygous p.Q124E MAPT variant, developed right-hand tremor at age 73 years." (PMID 23664753, 2013).
heart failure (1 paper, 2023). Inability of the heart to pump blood at an adequate rate to meet tissue metabolic requirements. "Hub genes including LRRK2, BMI1, KBTBD7, and FFAR2 were associated with the risk of heart failure." (PMID 38137330, 2023).
hemangioma (1 paper, 2016). A benign vascular lesion characterized by the formation of capillary-sized or cavernous vascular channels. "By scrutinizing peripheral organs of a LRRK2 knockout mouse line, we found that these mice develop age-dependent hepatic growths similar to hemangiomas." (PMID 27872856, 2016). "We examined HIF-2α expression by immunohistochemistry and found an apparent increase of HIF-2α signal in the nuclei of numerous cells surrounding the vascularized vessels in the livers of hemangioma- (HA-) positive LRRK2−/− mice (HA+)." (PMID 27872856, 2016). "Similarly, the expression of the HIF-2α target gene EPO was dramatically increased (reactivated) in the livers of HA-positive LRRK2−/− mice, suggesting a close correlation of EPO expression and the formation of hemangiomas in LRRK2−/− mice." (PMID 27872856, 2016). "In livers of these hemangioma-positive LRRK2 knockout mice, we detected an increased expression of the HIF-2α protein and significant reactivation of the expression of the HIF-2α target gene erythropoietin (EPO), a finding consistent with a role of the HIF-2α pathway in blood vessel vascularization." (PMID 27872856, 2016). "In this study, we report the identification of hemangioma-like growths in the livers of old LRRK2−/− mice and found that LRRK2 could affect the expression of EPO in the livers and kidneys of these mice." (PMID 27872856, 2016).
Hepatic hemangioma (1 paper, 2016). A congenital vascular malformation in the liver composed of masses of blood vessels that are atypical or irregular in arrangement and size. "Furthermore, the implication of LRRK2 in this process provides a new insight into the genetics of hepatic hemangiomas." (PMID 27872856, 2016). "We found that 33% of LRRK2−/− mice after the age of 19 months develop liver growths that are similar to hepatic hemangiomas, suggesting that LRRK2 might have an age-dependent function in affecting either erythropoiesis or angiogenesis in mice." (PMID 27872856, 2016). "In short, we found that LRRK2 could affect EPO expression in the kidneys and livers of aged mice, which might be related to the formation of hepatic hemangiomas." (PMID 27872856, 2016).
Hyperinsulinemia (1 paper, 2025). An increased concentration of insulin in the blood. "The LRRK2 G2019S mice show an overt metabolic defect, characterised by mild hypoglycaemia and hyperinsulinemia, a phenotype not previously observed in other LRRK2-related PD models." (PMID 40676250, 2025).
Hypertension (1 paper, 2020). The presence of chronic increased pressure in the systemic arterial system. "Hypertension was associated with age and LRRK2-PD status, which accounted for 34.9% of the variance." (PMID 32518334, 2020).
Hypokinesia (1 paper, 2023). Abnormally diminished motor activity. "In this respect, LRRK2 rodents greatly differ from classical toxin-induced rodent models, where overt nigro-striatal degeneration and hypokinesia are induced by acute administration of 6-OHDA or acute/subacute/chronic administration of MPTP." (PMID 37601008, 2023).
hypothyroidism (1 paper, 2013). Abnormally low levels of thyroid hormone. "LRRK2 deficiency can also be directly linked, via PRDX3, to the potential dysregulation of iodothyronine deiodinase, type III (DIO3), plausibly leading to hypothyroidism via conversion of T4 and T3 to inactive derivatives." (PMID 23799078, 2013).
injury (1 paper, 2022). Damage inflicted on the body as the direct or indirect result of an external force, with or without disruption of structural continuity. "Various types of TBI models indicated that LRRK2 worsens neuronal cell death, neuroinflammation, and behavioral deficits induced by brain injury, which could be alleviated after application of LRRK2 inhibitor." (PMID 35401152, 2022).
Juvenile onset (1 paper, 2022). Onset of signs or symptoms of disease between the age of 5 and 15 years. "Many pathological mutations have been reported in different genes that are causally linked to PD, but only two of them account for the vast majority: PRKN, encoding for parkin and representing the major cause of juvenile onset PD, and LRRK2 that encodes for leucine-rich repeat kinase 2 (LRRK2)." (PMID 35456037, 2022).
Kufor-Rakeb syndrome (1 paper, 2016). Kufor-Rakeb syndrome (KRS) is a rare genetic neurodegenerative disorder characterized by juvenile Parkinsonism, pyramidal degeneration (dystonia), supranuclear palsy, and cognitive impairment. "We identified 12 different additional rare variants evenly distributed within six different PD genes, including five different ATP13A2 non-Kufor-Rakeb syndrome (KRS) variants, in our LRRK2-positive cohort." (PMID 27798102, 2016).
leishmaniasis (1 paper, 2020). Infectious disease that is transmitted through the bite of hematophagous female phlebotomine sand flies. "Although the association between leishmaniasis and PD has remained unclear, LRRK2 deficiency in DCs enhances the production of pro-inflammatory cytokines and T-cell proliferation." (PMID 32164260, 2020).
liver diseases (1 paper, 2024). "However, few reports are available to elucidate the effect of LRRK2 on liver diseases, which is the original intention of this study." (PMID 38725082, 2024).
lupus-like syndrome (1 paper, 2019). "Furthermore, we demonstrated that LRRK2 promoted B cell terminal differentiation, humoral immune response and consequently lupus-like syndrome in a pristane-induced mouse model, thus implicating LRRK2 as a novel target in SLE therapy." (PMID 30670047, 2019).
Lysosomal disease (1 paper, 2020). "Our results therefore identify an underlying cellular pathway that represents a valid therapeutic target for PD, opening up possibilities for combination therapy against both LRRK2 and lysosomal disease mechanisms." (PMID 32375042, 2020).
malignant mesothelioma (1 paper, 2022). A malignant neoplasm of the pleura or peritoneum, arising from mesothelial cells. "Interestingly, somatic LRRK2 truncating or deletion mutations have been identified in malignant mesothelioma and LRRK2 expression was absent or downregulated in primary tumor cell lines." (PMID 35247252, 2022).
metachromatic leukodystrophy (1 paper, 2022). A rare lysosomal storage disorder characterized by intralysosomal accumulation of sulfatides in various tissues, leading to progressive deterioration of motor and neurocognitive function. "In four patients, rare heterozygous RDVs were detected in other neurodegeneration-associated genes, such as PRKN (PD), LRRK2 (PD), PARK7 (PD), C19ORF12 (NBIA), SPG11 (Spastic paraplegia-SP/ALS), and PSAP (Metachromatic leukodystrophy-MLD)." (PMID 35752680, 2022).
metastatic prostate carcinoma (1 paper, 2025). A carcinoma that arises from the prostate gland and has spread to other anatomic sites. "In the univariate analysis, several factors, namely T stage, GS, LRP6, and LRRK2, demonstrated strong associations with metastatic prostate cancer." (PMID 40660132, 2025). "Several gene mutations, including PIK3CA, LRP6, LRRK2, and BRCA2, were found to be associated with metastatic prostate cancer and BCR." (PMID 40660132, 2025). "Key predictors of metastatic prostate cancer identified were T stage, GS, PIK3CA, LRP6, LRRK2, and APOBEC3B deletion." (PMID 40660132, 2025). "Subsequently, the multivariate analysis, focusing on these previously identified significant factors, confirmed T stage, GS, LRP6, LRRK2, PIK3CA, and APOBEC3B deletion as significant predictors of metastatic prostate cancer." (PMID 40660132, 2025).
myelofibrosis (1 paper, 2022). A partial or complete replacement of the bone marrow stroma by fibrous tissue. "To extend the findings beyond birabresib, we also used pelabresib (CPI‐0610), a BET inhibitor currently in phase 3 trial for myelofibrosis (NCT04603495), to validate the synergism with LRRK2‐IN‐1." (PMID 36051080, 2022).
myocardial ischemia (1 paper, 2019). A disorder of cardiac function caused by insufficient blood flow to the muscle tissue of the heart. "Despite the fact, our findings may have implications for the diagnosis/prognosis and treatment of CAVS and the mitochondrial function-related proteins such as LRRK2 and ANK2 screened by CAVS bio-signal are important for the regulation of mitochondrial function in CAVS-induced myocardial ischemia." (PMID 30651404, 2019).
myotonic dystrophy type 1 (1 paper, 2017). Steinert disease, also known as myotonic dystrophy type 1, is a muscle disease characterized by myotonia and by multiorgan damage that combines various degrees of muscle weakness, arrhythmia and/or cardiac conduction disorders, cataract, endocrine damage, sleep disorders and baldness. "There was one p.A152T carrier among 57 LRRK2 carriers and no p.A152T carriers were identified among 20 patients with myotonic dystrophy type 1." (PMID 28594853, 2017).
narcolepsy (1 paper, 2020). A sleep disorder characterized by a tendency for excessive sleepiness during the day which occurs even after adequate sleep in the nighttime. "A correlation analysis with known genes associated with these disorders(LRRK2, HLA-DQB1, and HCRT) was used to query microarray data corresponding to brain regions known to be involved in PD and narcolepsy." (PMID 34745571, 2020).
nephritis (1 paper, 2019). Inflammation of renal tissue. "It was revealed that the severity of nephritis was ameliorated in Lrrk2−/− mice reflected by less glomeruli represented by less endocapillary or extracapillary proliferative lesions and sclerotic lesions." (PMID 30670047, 2019). "Negative correlations were observed between LRRK2 expression and serum C3 or C4 levels, two clinical features associated with SLE-related nephritis." (PMID 30670047, 2019).
Neurofibrillary tangles (1 paper, 2013). Pathological protein aggregates formed by hyperphosphorylation of a microtubule-associated protein known as tau, causing it to aggregate in an insoluble form. "Although we analyzed three different LRRK2 mutants, each of which has been implicated in familial PD with neurofibrillary tangle pathology, G2019S LRRK2 yielded the highest level of tau phosphorylation." (PMID 24113872, 2013).
obstructive sleep apnea (1 paper, 2015). "RLS, PLMS and obstructive sleep apnea were not prominent features in LRRK2-PD." (PMID 26177462, 2015).
pancolitis (1 paper, 2022). Ulcerative colitis that involves the entire colon. "When we analysed the SNPs located in LRRK2 gene, there were SNPs whose significance was higher when all IBD cases were analysed than analysing each subtype separately (rs4767970); and their significance was higher in ileal CD than in ileocolonic CD, and in left UC than in pancolitis UC (rs4767970)." (PMID 35232999, 2022).
periodontitis (1 paper, 2021). An acute or chronic inflammatory process that affects the tissues that surround and support the teeth. "Further MR studies using summary statistics from GWAS datasets of α synuclein and LRRK2 may explore the potential biological pathways between periodontitis and the risk towards PD." (PMID 34069479, 2021).
reovirus infection (1 paper, 2020). "On the other hand, the kinase inactive control, D1994S LRRK2 mutant mice had a higher survival rate due to reduced LRRK2 autophosphorylation with reovirus infection." (PMID 33291304, 2020).
restless legs syndrome (1 paper, 2022). A condition that occurs while resting or lying in bed; it is characterized by an irresistible urgency to move the legs to obtain relief from a strange and uncomfortable sensation in the legs. "Variants of GBA, LRRK2 and PRKN did not increase or decrease the risk and severity of excessive daytime sleepiness and restless legs syndrome in PD." (PMID 35395825, 2022).
seborrheic dermatitis (1 paper, 2024). A chronic, inflammatory skin disorder that affects the scalp, central face and skin folds; it is characterized by scaling and itching. "For instance, the association of seborrheic dermatitis with PD may originate from the shared genetic polymorphisms of GBA, LRRK2, and PINK1, which play a role in immune changes, lipid metabolism, and homeostasis of brain." (PMID 38468488, 2024).
Torsion dystonia (1 paper, 2024). Sustained involuntary muscle contractions that produce twisting and repetitive movements of the body. "Moreover, LRRK2 was associated with torsion dystonia (333.4, P = 3.79 × 10−4) and “Extrapyramidal disease and abnormal movement disorders” (333, P = 1.29 × 10−3) in BioMe BioBank." (PMID 38741190, 2024).
uveitis (1 paper, 2015). An inflammatory process affecting a part of or the entire uvea. "Here, we examined the possible involvement of LRRK2 in the pathogenesis of experimental autoimmune uveitis (EAU), an animal model for human uveitis, by testing Lrrk2 (-/-) mice for their capacity to develop this experimental eye disease and related immune responses." (PMID 26067490, 2015).
vitamin D deficiency (1 paper, 2024). A nutritional condition produced by a deficiency of VITAMIN D in the diet, insufficient production of vitamin D in the skin, inadequate absorption of vitamin D from the diet, or abnormal conversion of vitamin D to its bioactive metabolites. "In contrast, very little is known about LRRK2 and vitamin D deficiency, which is why we were intrigued that in both VDD datasets used in our study, LRRK2 is strongly upregulated." (PMID 38256187, 2024).
neurodegenerative disease (96 papers, 2006 to 2026). A disorder of the central nervous system characterized by gradual and progressive loss of neural tissue and neurologic function. "By altering the levels of its protein at its site of action, LRRK2 is closely linked to the pathological appendages of several neurodegenerative diseases." (PMID 40136428, 2025). "VPS35 is a critical component of the retromer cargo-selective complex and is implicated in neurodegenerative disease in patients with LRRK2 mutation." (PMID 40282191, 2025). "Autophagic dysregulation is linked to neurodegenerative diseases, including those associated with PD-related LRRK2 mutations." (PMID 39253496, 2025). "LRRK2 kinase activity is unambiguously linked to neurodegenerative diseases through pathogenic mutations that upregulate kinase activity and Rab phosphorylation." (PMID 40425780, 2025). "Glymphatic dysfunction is a shared pathway in various neurodegenerative diseases, including LRRK2-associated PD16." (PMID 38296953, 2024). "At the basis of neurodegenerative diseases, an emerging role is played by genetic mutations in the leucine-rich repeat kinase 2 (LRRK2) gene that cause increased LRRK2 activity with consequent alteration of neuronal autophagy pathways." (PMID 39519213, 2024). "Synapses have extensively been described to potentially play a critical role in the development of neurodegenerative diseases, including LRRK2-linked PD." (PMID 39726830, 2024). "Mutations in the LRRK2 gene represent genetic risk factors for the development of neurodegenerative diseases, particularly in Parkinson’s disease (PD)." (PMID 39519213, 2024). "Rab1 is directly linked to the pathogenesis of PD and other neurodegenerative diseases as a substrate of leucine-rich repeat kinase 2 (LRRK2), in which variants are the most common cause of familial and sporadic PD." (PMID 39769094, 2024). "Elucidating the mechanisms underlying the formation of pathological diversity is expected to contribute greatly to the elucidation of the pathophysiology of not only LRRK2-associated PD but also other neurodegenerative diseases." (PMID 37238714, 2023). "This was intriguing, as di-22:6-BMP has been established as a biomarker for a number of neurodegenerative diseases, including Niemann Pick type C and, more recently, LRRK2 G2019S mutation status." (PMID 35657605, 2022). "Parkinson's disease (PD) is the most common motor neurodegenerative disease, and the gene encoding the protein Leucine Rich Repeat Kinase 2 (LRRK2) is considered one of the most important genetic risk factors for PD." (PMID 32612495, 2020). "Further studies to validate the effect of PRDX2 on PD patients with LRRK2 kinase mutations and to investigate the neuroprotective effects of Chetomin in other neurodegenerative diseases will be warranted." (PMID 32990658, 2020). "Nonetheless, our findings that LRRK2 kinase plays an important role in Mn toxicity opens new avenues to explore therapeutic interventions to treat Mn toxicity, as well as other neurodegenerative diseases associated with aberrant LRRK2 function." (PMID 30645642, 2019). "Although the physiological function of LRRK2 protein remains largely elusive, increasing evidence suggests that it plays a role in innate immunity, a process that also has been implicated in neurodegenerative diseases, including PD." (PMID 28202666, 2017). "Understanding how PD mutations in LRRK2 affect its biochemical properties and functional activities is essential to elucidation of how LRRK2 dysfunction causes neurodegenerative disease." (PMID 25009464, 2014). "Recent association studies have linked LRRK2 with specific types of cancer, but like neurodegenerative diseases, the underlying mechanisms remain elusive." (PMID 24427314, 2014).